ALK (ALK receptor tyrosine kinase)
Diseases named in the same sentence as ALK in open-access papers (continued):
Sharing a sentence is not in itself a finding about the gene and the disease.
lung cancer (continued). "The success of EGFR and ALK inhibitor therapies in lung cancer patients with EGFR mutations and EML4-ALK translocations initiated the era of targeted therapy in advanced NSCLC and shifted treatment from platinum-based chemotherapy to molecularly targeted therapy." (PMID 25789627, 2015). "ALK is a receptor tyrosine kinase that has previously been associated with multiple cancer types and is an activating mutation in many types of lung cancer." (PMID 26405815, 2015). "We analyzed 214 mutations across 26 lung cancer-associated genes and three fusion genes using the MassARRAY® LungCarta Panel and the ALK, ROS1, and RET fusion assays in 198 consecutively resected lung adenocarcinomas from never-smoker females at a single institution." (PMID 25760072, 2015). "Although many molecular genetic studies have implicated certain genetic mutations in non-small cell lung cancer (NSCLC), including mutations in the EGFR, PIK3CA, BRAF, KRAS, and ALK genes, only a few studies have focused on the genetic events associated with salivary gland-type lung carcinomas." (PMID 26373952, 2015). "We analyzed patients with lung cancer with nodular GGOs to investigate the correlation between biomarker status and clinicopathological and radiologic characteristics and to determine the roles of ALK rearrangements and EGFR mutations in nGGOs." (PMID 24885886, 2014). "Thus, the ALK test should be performed promptly in accordance with the College of American Pathologists, International Association for the Study of Lung Cancer and Association for Molecular Pathology (CAP/IASLC/AMP) guidelines." (PMID 25295103, 2014). "Of the cases with clinical data available, ALK-positive lung cancers were associated with younger age compared with the common driver mutation group (p = 0.023), but age in ALK-positive group was not significantly difference from the pan-negative group (p = 0.83)." (PMID 23922677, 2013). "KT has created a novel diagnostic method to detect ALK fusion positive lung cancer." (PMID 23289484, 2013). "ALK, a member of the insulin receptor superfamily of receptor tyrosine kinases, is composed of 29 exons, with exons 20–29 encoding the tyrosine kinase domain ALK fusions are primarily found in lung cancer, where they occur with a prevalence of approximately 5%." (PMID 39906487, 2024). "Similar findings were observed in the current study, wherein crizotinib was the most common first-line treatment for ALK mutation-positive lung cancer patients, which may be explained by the reimbursement guidelines on ALK-TKIs by the Taiwan National Health Insurance Administration." (PMID 37007097, 2023). "In addition, the VTE risk is particularly high in ALK-positive lung cancer." (PMID 36089919, 2022). "A low TMB may also explain the limited efficacy of ICIs in EGFR-/ALK-mutated lung cancer." (PMID 35407463, 2022). "Interestingly, we demonstrated that PI3K/AKT signaling pathway, EGFR tyrosine kinase inhibitor resistance, non-small cell lung cancer and osteoclast differentiation were associated with ALK-positive lung cancer, all KEGG terms are statically significant (adjusted P value < 0.05)." (PMID 34234236, 2021). "Similarly, ExoDx®Lung (ALK)—validated in the Exosome Diagnostics CLIA laboratory—isolates and analyzes exosomal RNA contained in blood specimens for the purpose of detecting EML4-ALK fusion transcripts in the plasma of lung cancer patients whose primary tumors carry this type of mutation." (PMID 33803776, 2021). "Therefore, STAT3 activation induced by LDOC1 silencing may be associated with genetic abnormalities of EGFR and ALK and may exert a synergistic effect in lung cancer; this topic may be worth exploring in the future." (PMID 30634502, 2019).
lung cancer (continued). "In 2011, the Vysis Break Apart ALK fluorescence in situ hybridization (FISH) assay was approved by the United States Food and Drug Administration as a companion diagnostic for detecting ALK rearrangement in lung cancer patients who may benefit from treatment of tyrosine kinase inhibitor therapy." (PMID 31412611, 2019). "Therefore, IHC tests for ALK, such as those using the Ventana and N-Histofine kits, could be sufficiently reliable diagnostic methods in the treatment of patients with lung cancer using ALK-TKIs." (PMID 30943926, 2019). "About 5% of non-small cell lung cancers have been found to have a rearrangement in the ALK gene, and three targeted chemotherapy agents—crizotinib (Xalkori), ceritinib (Zykadia), and alectinib (Alecensa)—have been approved for patients with lung cancer demonstrating ALK mutations." (PMID 28045970, 2017). "Fusion between EML4 (echinoderm microtubule associated protein-like 4), a microtubule-associated protein, and ALK (anaplastic lymphoma kinase), a tyrosine kinase receptor belonging to the insulin receptor superfamily, was the first oncogenic fusion to be detected in lung cancer." (PMID 28872581, 2017). "Thus, using our homebrew PCR assay, we were able to accurately detect ALK rearrangements, which could be used for diagnostic screening of lung cancer patients." (PMID 28032602, 2017). "Additionally, most ALK-positive lung cancer is mutually exclusive to EGFR and KRAS mutations." (PMID 23936355, 2013). "The EML4-ALK L1152R mutation results in an amino acid substitution at position 1152 in ALK, from an L to R. L1152R has been detected in the tumor of a patient with ALK fusion-positive lung cancer who developed acquired resistance to the dual ALK/MET TKI crizotinib." (PMID 26316937, 2012). "Anaplastic lymphoma kinase (ALK) inhibitors have markedly improved outcomes in ALK-positive nonsmall-cell lung cancer (NSCLC)." (PMID 42038652, 2026). "Here, we found that molecular therapy targeted toward EGFR mutant, KRAS mutant, or ALK fusion lung cancer induced cholesterol biosynthesis, which promoted cancer cells to enter dormancy and thus escape drug killing." (PMID 41983392, 2026). "EML4-ALK-positive lung cancer represents an important molecular subtype of non-small-cell lung cancer (NSCLC) that initially responds to ALK inhibitors but invariably develops resistance, highlighting the need for novel targeted therapeutic strategies." (PMID 42280172, 2026). "We analyzed patients with unresectable stage III/IV disease without indications for radical radiotherapy and recurrent ALK-positive lung cancer who received alectinib as the primary ALK tyrosine kinase inhibitor between 2013 and 2021 at nine hospitals." (PMID 41529251, 2026). "Currently, there is limited evidence supporting ensartinib’s efficacy as a neoadjuvant treatment for locally advanced anaplastic lymphoma kinase (ALK)-positive non–small cell lung cancer (NSCLC)." (PMID 41776641, 2026). "Some anaplastic lymphoma kinase (ALK) gene rearrangement-positive lung cancers show early resistance, within 3 months, to alectinib." (PMID 41529251, 2026). "This was further supported by the evidence that RNase1/ALK co-expression is significantly correlated with worse survival in patients with lung cancer from the TCGA database." (PMID 40246819, 2025). "In summary, the interaction between ALK mutations and SMARCA4 deficiency in NSCLC highlights the complexity of lung cancer biology." (PMID 40416876, 2025). "Together, these results provide strong evidence that CAFs establish a protective niche for EML4-ALK-rearranged lung cancer cells toward ALK inhibition." (PMID 40524253, 2025). "Further studies are needed to establish optimal treatment protocols for patients with ALK-positive lung cancer." (PMID 41293380, 2025). "Together, these results suggested that the RNase1-driven-ALK-activation (RDAA) in lung cancer cells enhances cell proliferation, mobility and cellular transformation in vitro." (PMID 40246819, 2025).
lung cancer (continued). "The primary goal of the study is to establish a comprehensive nationwide clinical data and biospecimen repository for the study of ALK+ lung cancer biology." (PMID 40674592, 2025). "Few case reports have described the successful treatment of ALK-positive lung cancer with immune checkpoint inhibitors." (PMID 40660550, 2025). "This review is intended to bridge this gap by explaining in one article, in simple terms, important molecular aspects of ALK‐positive lung cancer and therapeutic strategies for its treatment." (PMID 41213866, 2025). "It is known that genomic biomarker‐directed indications, such as crizotinib treating ALK positive non‐small cell lung cancer, have strength in tailoring treatments for individual patients by testing their gene alterations." (PMID 40230311, 2025). "In recent years, extensive genomic characterization has revealed various actionable mutations in lung cancer, including epidermal growth factor receptor (EGFR), Kirsten rat sarcoma virus (KRAS), and anaplastic lymphoma kinase (ALK) mutations." (PMID 40647542, 2025). "In lung cancer, particularly non-small cell lung cancer (NSCLC), oncogenic alterations such as mutations in KRAS, EGFR, BRAF, and ALK rearrangements activate key signaling cascades, most notably the RAS–RAF–MEK–ERK and PI3K-AKT–mTOR pathways." (PMID 40823246, 2025). "For instance, capturing ALK or ROS1 fusion breakpoints in EV-DNA from lung cancer patients allow identification of candidates for ALK/ROS1 inhibitors even when tissue biopsy is infeasible." (PMID 41301080, 2025). "ALK inhibitor treatment of ALK‐fusion‐positive non‐small cell lung cancer cells leads to drug‐tolerant persister (DTP) cells with increased reactive oxygen species (ROS)." (PMID 39369284, 2025). "This first reported case of ALK-positive lung cancer in a CF patient highlights the need to consider malignancy in atypical exacerbations and to be mindful of potential interactions between ALK inhibitors and CFTR function." (PMID 40563468, 2025). "Despite advances in ALK inhibitors for ALK fusion-positive (ALK+) non–small-cell lung cancer (NSCLC), drug resistance remains a challenge." (PMID 40674592, 2025). "Current therapeutic strategies to overcome immune escape in ALK-targeted therapy-resistant lung cancer mainly involve immunotherapy and combination therapy." (PMID 40873540, 2025). "At the time of diagnosis of advanced ALK+ lung cancer, 22 (28%) patients presented with intrathoracic disease only and 56 (70%) patients with extrathoracic and intrathoracic metastases at baseline, with a median of 3 metastatic sites of disease (range: 2-6)." (PMID 40674592, 2025). "In this study, we established an ALK-mutant lung cancer cell line that was unstably resistant to alectinib, the second-generation ALK inhibitor." (PMID 40234387, 2025). "With the emergence of targeted therapies such as the third-generation EGFR-TKIs and the second-generation ALK-TKIs, as well as the rise of immunotherapy, the treatment pattern of lung cancer has undergone revolutionary changes." (PMID 41002559, 2025). "ALK (Anaplastic Lymphoma Kinase)‐positive NSCLC is a unique molecular subtype of lung cancer involving the rearrangement of the ALK gene (see later sections of the review for detail)." (PMID 41213866, 2025). "The years of diagnosis for advanced ALK+ lung cancer ranged from 2011 to 2022, with a median diagnosis year of 2019." (PMID 40674592, 2025). "While INI1-deficient lung cancer rarely coexists with EGFR, ALK, or other oncogenic driver mutations, comprehensive genetic profiling (CGP) remains essential for guiding treatment decisions, particularly in advanced-stage patients." (PMID 40291911, 2025). "As the first-generation anaplastic lymphoma kinase (ALK) inhibitor, crizotinib-induced grade 3/4 neutropenia was reported in 0%–30% of patients with lung cancer, while the rate of the second-/third-generation was reported as 1.1% and <1%, respectively." (PMID 41041640, 2025).
lung cancer (continued). "ALK is a receptor tyrosine kinase whose aberrant activation in lung cancer promotes cell proliferation, survival, and metastasis." (PMID 40873540, 2025). "The driver gene status of lung cancer, such as the echinoderm microtubule-associated protein-like 4 (EML4)-ALK fusion, highlights the heterogeneity of tumors at the molecular level." (PMID 40606995, 2025). "Anaplastic lymphoma kinase (ALK) gene rearrangements are observed in approximately 2-7% of NSCLC patients and have been established as a key driver mutation in lung cancer, particularly prevalent in younger patients and those with no smoking history." (PMID 40376587, 2025). "In recent years, precision treatment for lung cancer has gradually been applied in clinical settings, particularly in patients with EGFR mutations and ALK gene fusions." (PMID 41269529, 2025). "Following this discovery, multiple ALK inhibitors (ALKi) have been developed, and their efficacy has been assessed in lung cancer patients." (PMID 40227636, 2025). "Given the patient’s adverse reaction to chemoimmunotherapy and the limited efficacy of immunotherapy in ALK-related lung cancer, alectinib was a rational choice." (PMID 41293380, 2025). "In our study, we also found that ACACA expression is related to mutations of common driver genes in NSCLC, which agrees with recent research that common driver gene mutations in lung cancer, such as KRAS, EGFR, ROS1 and ALK, are closely related to metabolism." (PMID 41169354, 2025). "Similar to the therapeutic outcomes observed in EML4-ALK-positive lung cancer, patients with NPM-ALK-positive lymphomas have shown significant responsiveness to all generations of ALK inhibitors." (PMID 40584293, 2025). "Testing for ALK rearrangements now determines eligibility for ALK inhibitors, thereby enhancing progression‐free survival rates in lung cancer." (PMID 40636286, 2025). "Rearrangements of anaplastic lymphoma kinase (ALK) in lung cancer have spurred the development of ALK inhibitors, such as crizotinib and alectinib." (PMID 40636286, 2025). "In ALK‐positive lung cancer cells an abnormal configuration in the DNA was discovered, which resulted in the aberrant production of ALK in these cells." (PMID 41213866, 2025). "The challenge remains in subtypes of lung cancer patients that harbor driver mutations like EGFR, ALK, and ROS1 mutations." (PMID 39932765, 2025). "Immune checkpoint inhibitors are generally considered to be ineffective in chemotherapy for anaplastic lymphoma kinase (ALK)-positive lung cancer." (PMID 40660550, 2025). "Lung cancer patients with an anaplastic lymphoma kinase (ALK)-fusion can be treated effectively with ALK inhibitors." (PMID 40227636, 2025). "Anaplastic lymphoma kinase (ALK)-positive lung cancer is relatively rare and is prevalent among those with minimal or no tobacco exposure." (PMID 40422509, 2025). "Since its approval, it has revolutionized therapy for patients with ALK‐rearranged non‐small cell lung cancer (NSCLC), a subtype comprising 4%–7% of all NSCLC cases." (PMID 40542555, 2025). "Targeted therapies, particularly sequential TKIs, have transformed the management of ALK-positive lung cancer, significantly prolonging patient survival." (PMID 40422509, 2025). "The author hopes that this article will be interesting, informative and valuable to patients with ALK‐positive lung cancer, their families, friends, carers, and medical teams." (PMID 41213866, 2025). "Next, mice subcutaneously injected with H1299 control (without RNase1 expression), RDAA (ALK and RNase1 co-expression), or ALK mut lung cancer cells (EML4-ALK expression) were treated with ceritinib for two weeks (25 mg/kg/day)." (PMID 40246819, 2025). "Most of the studies developed models for the prediction of EGFR, followed by PD-L1 and ALK biomarkers in lung cancer." (PMID 40078179, 2025).
lung cancer (continued). "Regarding genetics, among the 3 common lung cancer gene variants (EGFR mutation, KRAS mutation, and EML4/ALK rearrangement), EML4/ALK rearrangement is considered to be a high-risk factor for the development of PE." (PMID 39754212, 2025). "Case 2: A 28-year-old female with ALK-positive non–small cell lung cancer presents with severe respiratory compromise due to extensive mediastinal disease and high-output chylothorax (>1 L/day) refractory to conventional therapy." (PMID 40421092, 2025). "This discovery provides a new therapeutic option for the treatment of patients with ROS1- or ALK-positive lung cancer." (PMID 40584293, 2025). "ALK-TKI therapy has significantly improved the prognosis of ALK-positive lung cancer patients, making ALK test a routine examination in most NSCLC cases." (PMID 40853979, 2025). "Recently, many studies have explored the relationship between EGFR and ALK gene rearrangements and the imaging and pathological features of lung cancer, but there are many controversies." (PMID 41020204, 2025). "Among those, only four lung cancer cell lines exhibited RNase1 and ALK co-expression with ALK phosphorylation, suggesting that RNase1 is required for ALK activation in lung cancer cells." (PMID 40246819, 2025). "ALK has been extensively studied in non‐small cell lung cancer, and the FDA has also approved five ALK inhibitors—alectinib, bugatinib, seretinib, clozotinib, and lorlatinib—for non‐small cell lung cancer with abnormal ALK expression." (PMID 39780907, 2025). "Despite the progress made in understanding and targeting ALK fusions in non-lung cancers, challenges remain in optimizing treatment strategies and overcoming resistance to ALK inhibitors." (PMID 41246301, 2025). "We hope that the anticancer efficacy of Iruplinalkib will be recognized globally and that it will become accessible to ALK-positive lung cancer patients worldwide." (PMID 40786512, 2025). "ALK fusions, such as the classic EML4‐ALK, are known drivers of lung cancer and effective therapeutic targets." (PMID 40151836, 2025). "In patients with lung cancer, ALK was detected in 14% (17/118), CMET was detected in 61% (78/128), HER2 was detected in 73% (16/22), and RET was detected in 4% (4/90)." (PMID 40075672, 2025). "This study highlights a critical role for CAFs in mediating resistance to ALK-TKIs by reprogramming lipid metabolism in ALK-rearranged lung cancer cells." (PMID 40524253, 2025). "The results from in vitro and in vivo studies demonstrated that ALK inhibitors are also effective in RDAA lung cancers, suggesting that the RDAA is not only an oncogenic driver but also an effective therapeutic target." (PMID 40246819, 2025). "In our cohort, among the patients with lung cancer, ALK was detected in 14% (17/118), and c-MET was detected in 61% (78/128)." (PMID 40075672, 2025). "Tobacco is a major carcinogen linked to lung cancer, but other genetic triggers, particularly mutations in KRAS, EGFR, ALK, BRAF, RET, MET and ROS1, are also central to its development." (PMID 40556802, 2025). "Crizotinib is an ATP-competitive inhibitor of ALK and Met tyrosine kinases, approved for lung cancer and lymphoma that are ALK-positive." (PMID 40507292, 2025). "used second‐generation sequencing, Sanger sequencing, and quantitative PCR to detect mutations in common lung cancer driver genes such as EGFR and ALK in 24 PACC patients, and the results showed that all patients had no mutations in common driver genes." (PMID 39828507, 2025). "ALK inhibitors can enhance the immunogenicity of ALK-positive lung cancer cells by altering the surface antigens, which can potentially improve the efficacy of ICIs when used in combination." (PMID 41472727, 2025). "A retrospective study indicated that NSCLC patients with EGFR mutations experience a higher incidence of arterial thrombotic events, whereas those with ALK-positive lung cancer are more prone to venous events." (PMID 41426325, 2025).